CDCA3 (cell division cycle associated 3)
Diseases named in the same sentence as CDCA3 in open-access papers (continued):
Sharing a sentence is not in itself a finding about the gene and the disease.
infection (5 papers, 2010 to 2025). The state of being infected such as from the introduction of a foreign agent such as serum, vaccine, antigenic substance or organism. "Numerous CDC genes are differentially expressed in the lung tissue of mice recovering from an acute PVM infection, including Cdc20, Cdc20b, Cdca3, Cdca4, and Cdca7." (PMID 34959580, 2021).
adenocarcinoma (3 papers, 2012 to 2021). A common cancer characterized by the presence of malignant glandular cells. "We have previously identified that cell division cycle-associated protein 3 (CDCA3) is elevated in adenocarcinoma (LUAD) and correlates with sensitivity to platinum-based chemotherapy." (PMID 34572879, 2021).
digestive tumours (1 paper, 2020). "Published articles about CDCA3 mainly focused on the role of CDCA3 in cell cycle regulation and drug resistance in digestive tumours and lung cancer." (PMID 32641718, 2020).
CDCA3 also shares sentences with these, for which no sentence is quoted: melanoma (3 papers); cholangiocarcinoma (2); glomerulosclerosis (2); viral infection (2); adrenocortical carcinoma (1); Barrett adenocarcinoma (1); bladder tumor (1); cardiovascular disease (1); cervical cancer (1); cervical squamous cell carcinoma (1); Cirrhosis (1); colon adenocarcinoma (1); complement deficiencies (1); COVID-19 (1); endometrioid adenocarcinoma (1); Fanconi anemia (1); head and neck squamous cell carcinoma (1); Hepatitis (1); hepatitis B (1); infectious disease (1); infertile (1); invasive lobular breast carcinoma (1); kidney chromophobe (1); kidney disease (1); lung squamous cell carcinoma (1); Maturity onset diabetes (1); meningococcal infection (1); mesothelioma (1); oral premalignant lesions (1); pancreatic adenocarcinoma (1).
A further 8 diseases each share a sentence with CDCA3 in 1 paper.